NR4A2 (nuclear receptor subfamily 4 group A member 2)
Diseases named in the same sentence as NR4A2 in open-access papers (continued):
Sharing a sentence is not in itself a finding about the gene and the disease.
osteosclerosis (1 paper, 2017). Abnormally high bone density. "Therefore it would be of interest to investigate whether the downregulation of NR4A2 could account for the proinflammatory macrophage phenotype in PMF patients and ultimately contribute to the development of BM fibrosis and osteosclerosis." (PMID 28098757, 2017).
pancreatic adenocarcinoma (1 paper, 2013). "By microarray gene profiling we identified NR4A2 as a gastrin responsive gene in the pancreatic adenocarcinoma cell line AR42J." (PMID 24086717, 2013). "Genome-wide time series experiments identified NR4A2 as a gastrin responsive gene in the pancreatic adenocarcinoma cell line AR42J." (PMID 24086717, 2013).
placental disease (1 paper, 2021). "Our in vitro models simulate conditions that drive placental dysfunction, offering insight into whether NR4A2 has a role in placental development, and the development of placental disease." (PMID 34667209, 2021).
pulmonary arterial hypertension (1 paper, 2025). Pulmonary arterial hypertension (PAH) is a group of diseases characterized by mean pulmonary artery pressure >20 mmHg and elevated pulmonary arterial resistance leading to right heart failure. "In patients with pulmonary arterial hypertension (PAH), the pulmonary artery smooth muscle cells (PASMCs) exhibited increased proliferation and survival and decreased expression of NR4A1, NR4A2, and NR4A3 (protein and mRNA) compared to normal lung PASMCs." (PMID 40871737, 2025).
rectum adenocarcinoma (1 paper, 2016). An adenocarcinoma arising from the rectum. "Furthermore, by analyzing a dataset from 97 patient samples with rectum adenocarcinoma, we found that the expression of NR4A2 and miR-34a was inversely correlated to a similar extent as other miR-34 targets AXL37 and SIRT124." (PMID 27121375, 2016).
salivary carcinoma (1 paper, 2024). "Nevertheless, given the limitations of this study which includes the lack of testing for NR4A3 (NOR1) or NR4A2 (NURR1) expression, a non-secretory salivary carcinoma cannot be entirely excluded in those cases without typical 1F1O1G rearrangements." (PMID 39101978, 2024).
salivary gland acinic cell carcinoma (1 paper, 2020). A carcinoma of the salivary gland characterized by serous acinar cell differentiation. "We report that most, if not all salivary gland acinic cell carcinomas (AcCC) harbor translocations that result in activation of the NR4A3 or NR4A2 genes." (PMID 32867110, 2020).
secondary progressive multiple sclerosis (1 paper, 2024). A multiple sclerosis with a clinical course characterized by a progressive accumulation of neurological disability, independent of relapses, following an initial relapsing-remitting (RR) phase. "The opposite is true for secondary progressive multiple sclerosis (SPMS), where CNS-resident EOMES+GZMB+NR4A2+CD4+ T cells correlate with active progressive disease." (PMID 39025930, 2024).
Splenomegaly (1 paper, 2022). Abnormal increased size of the spleen. "Transfer of NRP1+PD‐1+ Foxp3− Th cell elicited disease progression in protected male BXSB.Yaa Nr4a2 cKO mice, with splenomegaly and increases in serum antibodies, including ANA." (PMID 36069030, 2022).
steatosis (1 paper, 2024). Increased lipid within the cytoplasm of cells. "Similarly, NR4A2 overexpression was found to promote the progression of steatosis to NASH, while specific knockdown of NR4A2 in the liver protected mice from diet-induced NASH." (PMID 39287256, 2024).
Stillbirth (1 paper, 2020). Death of the fetus in utero after at least 22 weeks of gestation. "Circulating NR4A2, EMP1, and RCBTB2 mRNA were differentially regulated in another cohort destined for stillbirth, compared to ongoing pregnancies." (PMID 32438913, 2020).
viral infection (1 paper, 2022). "Moreover, in line with increased TCR signaling during chronic viral infection, we observed a conserved increase in the expression of AP-1 family members Jund and Junb, as well as in Cd69, Nr4a2, and Tox gene expression across all CD4+ T cell subsets during LCMV Cl13 infection." (PMID 36255051, 2022).
tumor (90 papers, 2008 to 2026). "Of note, several negative regulators of anti-tumor responses were down-regulated in CUL5 KO cells including exhaustion-associated biomarkers (NR4A2, PDCD1 and CD160), myeloid-derived suppressive cell promoting cytokine CSF2, and pro-apoptosis factor BCL2L11." (PMID 38242867, 2024). "NR4A2 is also associated with tumor proliferation, migration, and invasion." (PMID 36187094, 2022). "In addition, the detection by immunohistochemistry of high NR4A2 expression in tumor tissue was associated with worse survival rates in patients receiving post-operative 5-FU-based chemotherapy." (PMID 32751679, 2020). "To confirm that antigen-mediated control of transgene expression was maintained in vivo, we adoptively transferred NR4A2/NGFR human CAR T cells into OVCAR-3 tumor bearing mice and observed tumor-site specific expression of NGFR." (PMID 40610421, 2025). "In the presence of NECA during tumor stimulation, there was very little overlap between transcriptional changes across NR4A2/hA1R, A2ARKO and NR4A2KO CAR-T cells, highlighting the distinct transcriptional pathways associated with A1R signaling." (PMID 40610421, 2025). "This stress triggers the activation of nuclear receptor subfamily 4 group A member 2 (NR4A2), facilitating transcriptional alterations that enhance tumor proliferation." (PMID 40867215, 2025). "To highlight the potential for this approach to couple transgene expression to CAR activation, we first cocultured anti-Lewis Y CAR T cells engineered to express NGFR under the control of the NR4A2 promoter with Lewis Y+ tumor cells." (PMID 40610421, 2025). "Specifically, expression of transgenes via the endogenous NR4A2 promoter leads to stringent tumor-localized expression." (PMID 40610421, 2025). "This cellular response extends to the tumor microenvironment, where oxidative stress activates the NR4A2 protein in microglia, which, in turn, promotes tumor growth." (PMID 40867215, 2025). "CD49a+ cells express granzyme and perforin and play an anti-tumor role, whereas CD49a− cells express NR4A2 that promotes Treg differentiation, leading to tumor suppression." (PMID 41511327, 2025). "A recent study demonstrated that oxidative stress drives tumor progression through the activation of NR4A2-SQLE in microglia." (PMID 39763673, 2024). "Sixthly, the tumor-promoting mechanism of NR4A2 in ESCC warrants urgent investigation, given its paradoxical roles in cancer as reported in previous studies." (PMID 38570607, 2024). "IHC analysis of DLBCL samples in a TMA showed that NR4A2 protein was expressed in the tumor cells of almost all DLBCL samples with different levels of expression between the samples." (PMID 36831639, 2023). "The NR4A2 gene was found to be of particular interest since members of the NR4A family of genes have been described to act as tumor suppressors in lymphoid malignancies." (PMID 36831639, 2023). "In the effective treatment group, the expression of inflammation, cytokines, and Toll-receptor-related genes (such as FOS, CCL4, and NR4A2) increased in the CD8+ T cells in tumor tissues after treatment." (PMID 37762493, 2023). "The ieILC-1 has two subsets, CD49a+CD103+ that prevents tumor growth, and CD49a-CD103+NR4A2 that favors tumor growth." (PMID 35632488, 2022). "Collectively, these data revealed that Nr4a factors, particularly Nr4a1 and Nr4a2, play important roles in the maintenance of tumor Treg cells." (PMID 35514961, 2022). "NR4A2 is a member of the Nur77 orphan receptor subfamily, which plays a critical role in human tumor cell survival." (PMID 34903206, 2021). "NR4A2 inhibits apoptosis and activates the promoter of osteopontin, an inflammatory mediator that affects tumor progression and angiogenesis." (PMID 32751679, 2020). "Previous studies show that high expression of NR4A2, BTNL9, FOXP1, or PDE4D can antagonize immune response or is associated with tumor progression." (PMID 30911684, 2019).
tumor (continued). "Based on the known roles of NR4A2 in oncogenic processes within cancer, we posited that a likely candidate miRNA would be one that harbored tumor-suppressive functions and was downregulated in cancer, consequently leading to upregulation of NR4A2." (PMID 27121375, 2016). "We find that sustained expression of NR4A2 inhibits gastrin induced invasiveness, which is congruent with a tumor suppressor function of NR4A2 in AGS-GR cells." (PMID 24086717, 2013). "The pattern was rather dominated by a general expression of NR4A2 in tumor cells, showing mixed nuclear or cytoplasmic localization and variable intensities." (PMID 24086717, 2013). "Knock-down experiments with siRNA targeting NR4A2 increase migration of gastrin treated adenocarcinoma AGS-GR cells, while ectopically expressed NR4A2 increases apoptosis and hampers gastrin induced invasion, indicating a tumor suppressor function of NR4A2." (PMID 24086717, 2013). "To restrict A1R expression to the tumor site we therefore utilized a CRISPR knock-in approach to drive A1R expression under the control of the endogenous NR4A2 promoter, which we have previously demonstrated to be highly tumor-restricted in its transcriptional activity." (PMID 40610421, 2025). "To further interrogate the underlying biology of NR4A2/hA1R engineered CAR T cells we performed bulk ATAC-seq of NR4A2/hA1R CAR T cells after OVCAR-3 tumor stimulation which demonstrated clear epigenetic changes in NR4A2/A1R engineered CAR T cells that were only apparent following activation." (PMID 40610421, 2025). "We utilized a xenograft tumor mouse model to verify the oncogenic role of NR4A2 in ESCC." (PMID 38570607, 2024). "Therefore, targeting inhibition of NR4A2 or SQLE suppressed tumor growth and reversed CD8+ T cell exhaustion." (PMID 38632627, 2024). "Importantly, eribulin promoted the shift of patient-derived intratumoral NK cells towards an anti-tumor CD49a+ CD103+ NK subset (ieILC1-like) while diminishing the dysfunctional NR4A2-expressing CD49a− NK subset." (PMID 39594830, 2024). "The same study showed that pharmacological inhibition of NR4A2 could delay tumor development, while targeting either NR4A2 or SQLE enhances the effectiveness of immune checkpoint inhibitors in animal models." (PMID 39763673, 2024). "NR4A2, for example, is known as a transcription factor involved in NK cell development and NK cells that express high levels of this transcription factor had a poor cytotoxic activity against tumor cells." (PMID 37662951, 2023). "NR4A2 protein expression in the tumor cells was confirmed by IHC." (PMID 36831639, 2023). "NR4A1 influences tumor cell proliferation, while NR4A2 promotes M2 polarization." (PMID 37533434, 2023). "Treg-specific Nr4a1 and Nr4a2 deficient mice have increased tumor resistance and pharmacological treatments that inhibit the expression of these NR4As in tumoral Treg cells result in improved CD8+ T cell functions and tumor control." (PMID 33597928, 2020). "In addition, we also discovered one tumor sample with a highly homologous gene, NR4A2, chromosomal translocation to the enhancer region on chromosome 4, suggesting possible redundant functions of NR4A2 for NR4A3." (PMID 32867110, 2020). "Likewise, a recent study reported double deletion of NR4A1/NR4A2 in CD8+ tumor-infiltrating lymphocytes (TILs) resulted in murine tumor eradication after transfer as well as expansion of TSL population with increased chromatin accessibility of several stem-like/memory-related genes." (PMID 39211052, 2024). "In studies on tumor-inoculated mice, it was shown that CAR-T cells deficient in both TOX and TOX2, or with triple KO of NR4A1, NR4A2, and NR4A3, had a greater anti-cancer activity and improved animal survival; therefore, targeting the TOX/NR4A axis may reduce the depletion of CAR-T cells in TME." (PMID 37296906, 2023).
tumor (continued). "However, there are not yet any studies describing whether these or other compounds may be able to mitigate the transcriptional or oncogenic activities of NR4A3 or NR4A2 in tumor cells." (PMID 32867110, 2020). "Critically, in contrast to our previous data with constitutively expressing A1R CAR T cells, the numbers of NR4A2/hA1R CAR T cells were equivalent to controls in both the spleen and the tumor at up to day 28 post therapy." (PMID 40610421, 2025). "In contrast, in most solid tumors, both NR4A1 and NR4A2 exhibit pro-oncogenic activity, whereas, in limited studies, NR4A3 exhibits either minimal activity or acts as a tumor suppressor." (PMID 40332813, 2025). "The first tumor-reactive subcluster, resident memory T cells (TRM), was characterized by specific expression of NR4A2, NR4A3, and TUBA4A, undertaking immune surveillance and immune activation." (PMID 40315321, 2025). "Integrative omics analysis highlights the potent influence of methionine/SAM on NR4A2 expression in a tumor-specific manner, mediated by the IGF2BP2-dependent stabilization of methylated NR4A2 mRNA." (PMID 38570607, 2024). "Bioinformatics analysis revealed that APOC1, CFH, LGALS1 and NUSAP1 were highly expressed in bone metastases compared to primary tumours, whereas ADRB2, NR4A2 and ZNF331 exhibited the opposite trend (p < 0.05)." (PMID 39098992, 2024). "Within the tumor-infiltrating CD4_4 cluster, we observed increased expression of the Th1 driver TBX21 (T-bet), activation marker LAG3 and NR4A2 and cytokine expression." (PMID 33504936, 2021). "Subsequent deletion of IRF8 in NR4A2/hA1R engineered CAR T cells abrogated the enhanced cytokine production in both serial and long-term stimulation assays and suppressed A1R driven enhanced tumor killing during the second round of long-term restimulation." (PMID 40610421, 2025). "Indeed, NR4A2/A1R engineered CAR T cells exhibited significantly increased expression of IFNγ, TNF and IL-2 secretion, primarily in CD8+ CAR T cells, following tumor cell coculture." (PMID 40610421, 2025). "High dietary methionine dramatically expedited the tumor growth of implanted control ESCC cells but not ESCC cells lacking NR4A2." (PMID 38570607, 2024). "Individually, both NR4A1 and NR4A2 exhibit pro-oncogenic activity in many solid tumors, whereas in many blood-derived cancers, NR4A1 and NR4A3 are classified as tumor suppressors based on the rapid development of acute myeloid leukemia observed in double knockout NR4A1−/−:NR4A3−/− mice." (PMID 38540704, 2024). "Moreover, Nr4a2-/- CD8+ CAR T cells showed reduced expression of exhaustion markers and demonstrated higher tumor regression and enhanced survival in tumor-bearing mice." (PMID 38514798, 2024). "However, triple knockout of Nr4a (including Nr4a1, Nr4a2, and Nr4a3) in CAR-T cells promoted tumor regression and prolonged the survival of tumor-bearing mice." (PMID 37596653, 2023). "NR4A2 and MUC5B protein expression in tumor cells was confirmed by IHC analysis of DLBCL samples." (PMID 36831639, 2023). "The top-ranked tumor-cell-specific DCI genes were PDE10A and NR4A2 involved in cAMP pathways." (PMID 37433798, 2023). "We found that CD8-GNLY effector T cells in high tumor infiltration group displayed increasing level of the serine/threonine kinase PIM family (PIM2 and PIM3), NR4A2/3, KLF4/6, BCL2, GPR183 and COTL1 compared to the ones from HD and low tumor infiltration group." (PMID 36532059, 2022). "In contrast, tumor T cells’ DEGs coded for heat shock proteins, such as HSPA6, HSPA1A, and HSPA1B in addition to genes related to T cell development and function, such as NR4A1 and NR4A2." (PMID 35534852, 2022). "Indeed, the Nr4a triple-knockout (Nr4a1, Nr4a2 and Nr4a3) in CAR TILs promoted tumor regression and prolonged the survival of tumor-bearing mice." (PMID 34639168, 2021).
tumor (continued). "Furthermore, NR4A2/hA1R engineered cells exhibited a similar frequency of TSCM CAR T cells in the spleen, indicating that linking A1R expression to CAR T cell activation at the tumor site overcame the deleterious effects on persistence." (PMID 40610421, 2025). "Additionally, under low dietary methionine conditions, NR4A2 abrogation did not further impede ESCC tumor growth and decline intratumoral expression of PCNA and Cyclin B1." (PMID 38570607, 2024). "Importantly, methionine specifically elicited NR4A2 expression in tumor cells, as there was no change in NR4A2 expression in the presence of methionine in a non-transformed esophageal epithelial cell line, Het-1A." (PMID 38570607, 2024). "Interestingly, in comparison to wild-type CAR T cells, the transfer of NR4A1, NR4A2, and NR4A3 triple knockout CAR T cells to tumor-bearing mice decreased the proportion of highly exhausted CAR T cells among the tumor-infiltrating lymphocytes and led to a better prognosis." (PMID 35606821, 2022). "NR4A2/A1R engineered CAR T cells elicited significantly enhanced CAR T cell efficacy in vivo and led to enhanced CAR T cell differentiation at the tumor site without any impact on persistence in the spleen or tumor." (PMID 40610421, 2025). "In contrast, the TF motifs (e.g., NR4A1, NR4A2, and NR4A3) orchestrating T-cell exhaustion were exclusively enriched in tumor-specific Tex cells but not in plaque-specific Tem cells." (PMID 38491170, 2024).